CYP24A1 (cytochrome P450 family 24 subfamily A member 1)
Diseases named in the same sentence as CYP24A1 in open-access papers (continued):
Sharing a sentence is not in itself a finding about the gene and the disease.
Hypercalcemia (continued). "Of note, only 13 participants exhibited increased serum ionized calcium, and the majority of our cohort did not demonstrate overt hypercalcemia, which may have further weakened the association between PTH and reduced CYP24A1 activity." (PMID 38765596, 2024). "Our findings suggested that these histone methylations may mediate, in part, the PRMT5 repression of 1,25(OH)2D3 induced Cyp24a1 transcription at times when protection against hypercalcemia is not needed." (PMID 37408241, 2023). "Autosomal recessive inheritance of mutations in the sodium-phosphate co-transporter NaPi2a, encoded by SLC34A1, cause idiopathic infantile hypercalcaemia (IIH), classified as hypercalcaemia, infantile 2 (HCINF2), in a subgroup of patients without CYP24A1 mutations." (PMID 31935940, 2020). "An alternative approach is to utilize nonsecosteroidal VDR agonists that are not predicted to be substrates for CYP24A1 metabolism and show greater discrimination between levels required to induce a desired biological response and those that induce hypercalcemia." (PMID 28591703, 2017). "In mice with CKD, intestinal Cyp24a1 deletion decreased PTH and FGF23 without precipitating hypercalcemia." (PMID 39688907, 2024). "Together, these data indicate that deletion of Cyp24a1 from the intestine is sufficient to augment local 1,25D effects and suppress PTH without precipitating hypercalcemia or altering systemic vitamin D levels." (PMID 39688907, 2024). "Using the VCaP TMPRSS2:ERG positive cell line as a model, we found that a nonsecosteroidal CYP24A1 resistant VDR agonist, VDRM2, substantially reduces growth of xenograft tumors without inducing hypercalcemia." (PMID 28591703, 2017). "Based on our data from mice fed a high calcium diet, we hypothesized that inhibiting intestinal CYP24A1 could restore 1,25D effects locally in the intestine and thereby attenuate secondary hyperparathyroidism in CKD without precipitating hypercalcemia." (PMID 39688907, 2024).
breast carcinoma (52 papers, 2007 to 2026). "For example, in breast cancer, high expression of CYP24A1 is associated with tumor progression, and amplification of CYP24A1 locus at 20q is an adverse prognostic factor for recurrence free survival in ER+ breast cancer." (PMID 40630116, 2025). "SNP rs2762934 in an intronic region of CYP24A1 was associated with an increased risk of breast cancer, ischemic stroke, and hypertension." (PMID 33802237, 2021). "First overexpression of CYP24A1 in breast cancer is associated with the amplification of chromosomal locus 20q13.2–20q13.3 containing the CYP24A1 gene, which has been also observed in other cancers, including colon malignancies." (PMID 29657326, 2018). "The two SNPs, rs2209314 and rs2762941, in CYP24A1 shown to be associated with racial differences in ER- breast cancer risk are intronic." (PMID 22480149, 2012). "Instead, we evaluated variants in vitamin D activity and major metabolism (VDR, CYP27B1, and CYP24A1) in relation to breast cancer risk, particularly in relation to self-reported race and estrogen receptor status." (PMID 22480149, 2012). "Our research does not support an independent association between selected polymorphisms in the VDR, GC, or CYP24A1 genes and postmenopausal breast cancer risk among US Caucasian women." (PMID 17244366, 2007). "None of the VDR genotypes or polymorphisms in the vitamin D-binding (GC) or CYP24A1 gene was significantly associated with overall postmenopausal breast cancer risk." (PMID 17244366, 2007). "For example, Ying Wei reported that CYP24A1-rs4809957 SNP was associated with an increased risk of breast cancer (allele A: OR = 1.27, 95% CI: 1.03–1.55, p = 0.024; A/A vs. G/G: OR = 1.80, 95% CI: 1.15–2.82, p = 0.010; recessive model: OR = 1.70, 95% CI: 1.12–2.58, p = 0.012)." (PMID 40630116, 2025). "TBX4 and CYP24A1 are overexpressed in breast cancer and are associated with breast cancer risk." (PMID 37426199, 2023). "This structural heterogeneity might be the potential mechanism that caused CYP24A1 to be significantly downregulated in breast cancer samples and participated in the specific molecular function of breast cancer." (PMID 34926308, 2021). "CYP24A1 presented a moderate diagnostic ability in breast cancer." (PMID 31548577, 2019). "However, for rs6013897 genotypes (located at the 24-hydroxylase gene (CYP24A1)) there was a significant association with breast cancer (P<0.05)." (PMID 22649517, 2012). "In this study, we found that relationships between breast cancer risk and variants in genes associated with vitamin D activity and metabolism, VDR and CYP24A1, differed depending upon self-reported race and that associations were most notable for risk of ER- breast cancer in both AA and EA women." (PMID 22480149, 2012). "Although VDR rs10783218 was marginally associated with a twofold increased risk of ER+ breast cancer among EA women and VDR rs3819545 was associated with a decreased risk of ER- breast cancer, several SNPs in CYP24A1 were highly significantly associated with risk of ER- breast cancer." (PMID 22480149, 2012). "Importantly, we found that rs2209314 and rs2762941 in CYP24A1 contributed significantly to the higher risk of ER- breast cancer in AA than EA women." (PMID 22480149, 2012). "Knockdown of CYP24A1 using shRNA in mammary tumour lines resulted in the suppression of the metabolism of vitamin D and abrogated tumour growth in vivo, supporting the hypothesis that deficiency of vitamin D could be related to breast cancer incidence." (PMID 33809117, 2021). "Furthermore, splicing variants of CYP24A1 have been reported in breast cancer cell lines, suggesting that distinct forms of the enzyme with altered properties may be expressed in tumors." (PMID 24982636, 2014). "Preliminary research into CYP24A1 has subtly indicated its linkage with several tumor types, though its precise role and implications in breast cancer have lingered in a somewhat nebulous state." (PMID 39068476, 2024).
breast carcinoma (continued). "Our work seeks to underscore the crucial involvement of CYP24A1 in breast cancer, providing novel insights into its probable therapeutic ramifications." (PMID 39068476, 2024). "In conclusion, this research has adeptly uncovered pivotal roles that CYP24A1 and TFPI2 undertake in breast cancer, and has established a predictively precise risk assessment model." (PMID 39068476, 2024). "This research aimed to elucidate the roles of CYP24A1 and TFPI2 genes in breast cancer and to formulate a predictive model for risk assessment with robust characteristics." (PMID 39068476, 2024). "Numerous studies have suggested the expression level of the CYP24A1 was abnormally increased in several cancers, such as breast cancer, ovarian cancer, cervix carcinoma, lung cancer, and colon cancer." (PMID 37670334, 2023). "Nevertheless, the significance of CYP24A1 expression level as an independent prognostic factor in breast cancer is still a matter of debate." (PMID 34003583, 2022). "Gastro-intestinal (n = 9) and prostate cancer bone metastases had a tendency towards having a high CYP24A1 protein expression, whereas, in particular, breast cancer bone metastases had a rather low CYP24A1 protein expression." (PMID 36362766, 2022). "In contrast, breast cancer patients with low-CYP24A1-expressing cancers had a reduced overall survival." (PMID 36362766, 2022). "In order to further decipher the molecular mechanism of CYP24A1, we identified three known breast cancer–related SNPs (rs4909959, rs2209314, rs22762941) according to the SNP4Disease database." (PMID 34926308, 2021). "The increased expression of CYP24A1 was demonstrated to be correlated with the advanced stages of prostate, colon, lung and breast cancers, stimulating resistance to vitamin D-mediated therapy." (PMID 34208589, 2021). "For example, two studies that profiled gene expression in response to 1,25D treatment of breast cancer explants in culture, which were primarily ER+ ductal carcinomas, revealed only four commonly regulated genes (CYP24A1, CLMN, EFTUD1, SERPINB1)." (PMID 34950835, 2021). "Firstly, it has been shown that overexpression of CYP24A1 in breast cancer is related to the amplification of chromosomal locus 20q13.2–20q13.3 comprising the CYP24A1 gene, that has been also found in other types of cancer, including colon malignancies." (PMID 34208589, 2021). "With the first identification of CYP24A1 in breast cancer as a candidate oncogene, an increased or decreased CYP24A1 expression has been identified distinctively in various cancers such as prostate, endometrial, and lung." (PMID 34191826, 2021). "CYP24A1, which reduces 1,25-OH-D to 25-OH-D, was shown to be present in 50% of breast cancer samples, whereas its expression is low in normal breast tissue (excluding luminal epithelial progenitors)." (PMID 34638264, 2021). "Previous research has also revealed aberrantly high levels of CYP24A1 in multiple kinds of cancer cells, including ovarian cancer, breast cancer, thyroid cancer, and glioma cells, thereby making them resistant to 1α,25(OH)2D3." (PMID 32850381, 2020). "This study aimed to identify the correlation between CYP24A1 mRNA expression and prognosis of breast cancer." (PMID 31548577, 2019). "The prognostic value of CYP24A1 in breast cancer was assessed using Kaplan–Meier curves and Cox analysis." (PMID 31548577, 2019). "CYP24A1 expression regulates cellular response to vitamin D, which has antitumor effects against breast cancer." (PMID 31548577, 2019). "CYP24A1 expression was an independent prognostic factor for patients with breast cancer as confirmed by univariate and multivariate Cox analyses (with 912 patients actually included in the multivariable Cox analyses)." (PMID 31548577, 2019). "The subsequent multivariate analysis (with 1087 patients actually included) validated that age, clinical stage and CYP24A1 expression were independent prognostic factors for overall survival of patients with breast cancer." (PMID 31548577, 2019).
breast carcinoma (continued). "Herein, we evaluated the correlation between CYP24A1 expression in breast cancer and clinicopathologic features through analysis of data from The Cancer Genome Atlas (TCGA) database." (PMID 31548577, 2019). "The present study focused on CYP24A1 mRNA expression and demonstrated the important role of CYP24A1 in breast cancer." (PMID 31548577, 2019). "The Cancer Genome Atlas database was used to study CYP24A1 mRNA expression in breast cancer, and Chi-squared tests were performed to test the correlation between clinical features and CYP24A1 expression." (PMID 31548577, 2019). "In contrast, overexpression of the catabolic enzyme CYP24A1 is fairly frequent in malignant cells and was even described as an oncogene in breast cancer screening." (PMID 30321335, 2019). "Deceased patients with breast cancer had lower CYP24A1 expression than living patients with breast cancer." (PMID 31548577, 2019). "CYP24A1 antagonizes the antitumoral actions of this vitamin and is known to be overexpressed in breast cancer tissue." (PMID 28003019, 2016). "This is similar to reports in human CRC18 and breast cancer, where CYP24A1 overexpression goes hand in hand with higher CYP27B1 levels." (PMID 26238339, 2016). "Gene targets in breast cancer samples, including CYP24A1, DPP4 and CA2, seem to be shared by both fibroblasts and epithelial cells." (PMID 23497279, 2013). "Although these SNPs have not been implicated previously in breast cancer, elevated expression of CYP24A1 was found in breast cancer tissues, indicating a potential role in breast cancer etiology." (PMID 22480149, 2012). "In contrast, astemizole inhibited basal CYP3A4 gene expression and blocked calcitriol-dependent CYP3A4 induction, in a similar manner as that observed for CYP24A1 in breast cancer cells." (PMID 22984610, 2012). "In summary, this is the first study to report the expression of the VDR, CYP27B1 and CYP24A1 in a series of normal breast, preneoplastic mammary lesions, breast carcinomas in situ and invasive tumours." (PMID 20831823, 2010). "Overall, our results on the expression of the VDR, CYP27B1 and CYP24A1 suggest that there is a deregulation of the Vitamin D metabolic and signalling pathways in breast cancer, in order to favour tumour progression." (PMID 20831823, 2010). "Low expression of CYP24A1 is correlated with poor prognosis in breast cancer." (PMID 38750571, 2024). "The expression of CYP24A1 has been found to be inversely correlated to the expression of miR-125b in breast cancer, suggesting that decreased levels of miR-125b may be responsible for CYP24A1 overexpression in cancer." (PMID 34208589, 2021). "In vitro and in vivo studies also showed that CYP24A1 has been deemed as a candidate oncogene in many cancers, such as ovarian cancer, colorectal cancer, prostate cancer, lung cancer, breast cancer, thyroid cancer, and so on." (PMID 34422647, 2021). "By analyzing the function and molecular mechanism of leading genes, we found that 16 key biomarkers of breast cancer might be related to prognosis and molecular diagnostics, including CYP24A1 and ABHD11-AS1." (PMID 34926308, 2021). "Overexpression of Cyp24a1 in mammary cells makes such animals more sensitive to breast cancer." (PMID 30321335, 2019). "CYP24A1 plays an important role in prognosis of breast cancer." (PMID 31548577, 2019). "Similar to results found in other cancers, including lung adenocarcinoma and colorectal cancer, CYP24A1 may be a promising biomarker in breast cancer." (PMID 31548577, 2019). "In addition, CYP24A1 expression was an independent prognostic factor of breast cancer, making it a promising biomarker with great potential in the near future." (PMID 31548577, 2019). "However, based on the complexity of the role of vitamin D in breast cancer, the specific function of CYP24A1 needs to be further elucidated by clinical trials in the future." (PMID 31548577, 2019). "The present study sheds light on the important role of CYP24A1 in breast cancer." (PMID 31548577, 2019).
breast carcinoma (continued). "Thus, CYP24A1 is thought to play an important role in breast cancer through the vitamin D signaling pathway." (PMID 31548577, 2019). "A nested case-control study within the Cancer Prevention study II (CPS-II) Nutrition Cohort examined the association between breast cancer and these four VDR SNPs (FokI, BsmI, ApaI, and TaqI), as well as SNPs in the 24-hydroxylase gene (CYP24A1) and vitamin D-binding protein gene (DBP)." (PMID 23533810, 2013). "However, genes of hot regions are linked to breast cancer disease such as BACH1, RAD51C, CYP24A1 and NCOA3." (PMID 23368971, 2013). "In AA women, four SNPs in VDR - rs12721364, rs2239186, rs886441, and rs11568820 (Cdx2) - but none in CYP24A1 were associated with breast cancer risk at a nominal significance level of 0.05." (PMID 22480149, 2012). "We found that four SNPs in VDR and two SNPs in CYP24A1 had differential associations with breast cancer by race (P for interaction was not more than 0.10)." (PMID 22480149, 2012). "It has also been described that the CYP24A1 gene is amplified in breast cancer." (PMID 20831823, 2010). "Diet did not modify the associations between GC or CYP24A1 gene polymorphisms and breast cancer risk (not shown)." (PMID 17244366, 2007). "In addition, in breast cancers CYP24A1 expression decreased during tumor development." (PMID 25334067, 2014). "In a case (n = 928)-control (n = 843) study of breast cancer in AA and EA women, we measured serum 25OHD levels in controls and tested associations between risk and tag single nucleotide polymorphisms (SNPs) in VDR, CYP24A1 and CYP27B1, particularly by ER status." (PMID 22480149, 2012). "In EA women, two SNPs in VDR - rs11608702 and rs7975332 (Apa1) - and three SNPs in CYP24A1 - rs912505, rs3787555, and rs2244719 - were associated with breast cancer risk (P < 0.05) but did not remain significant after multiple comparisons were controlled for (data not shown)." (PMID 22480149, 2012). "Variants in CYP2R1, CYP24A1, CYP27B1, and DBP have been reported to influence circulating 25(OH)D concentrations and provide evidence for a hypothesis that these polymorphisms may be associated with breast cancer risk by altering vitamin D metabolism and signaling." (PMID 42292230, 2026). "To further investigate the effects of CYP24A1 and TFPI2 on the tumorigenic capacity of breast cancer cells in vivo, we established a nude mouse xenograft animal model for breast cancer transplantation." (PMID 39068476, 2024). "Survival analysis was performed using Kaplan-Meier curves, and the results revealed a significant correlation between CYP24A1 and TFPI2 with the prognosis survival time of breast cancer patients." (PMID 39068476, 2024). "Further scientific exploration into the biological mechanics regulated by CYP24A1 and TFPI2 is imperative, focusing particularly on their impact on breast cancer cell proliferation, metastasis, and therapeutic responsiveness." (PMID 39068476, 2024). "Validation of the GEO dataset revealed a significant correlation between the expression of CYP24A1 and TFPI2 genes and the survival status of breast cancer patients." (PMID 39068476, 2024). "This will help validate the prognostic relevance of CYP24A1 and TFPI2 in a more diverse range of breast cancer cases, thus enhancing the generalizability and clinical utility of our findings." (PMID 39068476, 2024). "VDR influences the expression of ITGβ3, SLC1A1, KDR, BIRC3 and GLUL, exerting an antiproliferative phenotype, promotes CYP24A1, SERPINB1, EFTUD1, CLMN, KLK6—The three latter are related to better survival in breast cancer." (PMID 34638264, 2021). "Elevated expression of CYP24A1, an immediate target gene of VDR, has been observed in breast cancer cells with aberrant amplification of the chromosomal loci encoding the gene." (PMID 33809117, 2021).